ATM (ATM serine/threonine kinase)
Diseases named in the same sentence as ATM in open-access papers (continued):
Sharing a sentence is not in itself a finding about the gene and the disease.
cancer (continued). "Some germinal mutations cause the reduction of ATM expression or activation causing mild phenotype characterized by slower progression of neurological features, longer survival, chromosomal instability, and cancer predisposition." (PMID 34771661, 2021). "In addition, pan-cancer studies provide evidence for factors affecting predisposition to different cancer types, highlighting rare germline cancer susceptibility variants that affect tumour suppressor genes including ATM, BRCA1, BRCA2, BRIP1, and PALB24." (PMID 34253785, 2021). "Notably, loss of ATM, which is a frequent event in cancers, confers synthetic growth defects and PARPi sensitization in the absence of ALC1." (PMID 33333017, 2021). "Consequently, ATR inhibitors (ATRi) are in clinical development for the treatment of cancers, including tumours harbouring mutations in the related kinase ATM." (PMID 34329458, 2021). "It is known that AT patients also have an increased risk of cancer due to the loss of ATM function." (PMID 33912571, 2021). "Therefore, ATM mutations possibly make individuals susceptible to cancer and are harmful for physiological activity." (PMID 34124196, 2021). "We recently reported that the inhibition of the ATM/CHK2 pathway could activate the innate immunity of ARID1A-deficient cancers and enhance the anti-tumor effect of PD-L1 antibody." (PMID 34026622, 2021). "PARP inhibitors had a significant killing effect on many cancers with ATM deficient." (PMID 33705352, 2021). "L82 was also selectively toxic in BRCA2 deficient or ATM deficient cancer cells and 3D-spheroids." (PMID 34373746, 2021). "BRCA1 directly interacts with PR, and ATM mutates frequently in PR-positive cancers." (PMID 33891016, 2021). "We find that the number of mutated ATM/ATR residues varies widely from one cancer type to another." (PMID 33742106, 2021). "Together, our data suggest that removal or inhibition of ALC1 could be exploited in HRD- and/or ATM-deficient cancers, either alone or in combination with PARPi." (PMID 33333017, 2021). "A similar variant (ATM E2366 *) can propagate mutations associated with predispositions to cancer." (PMID 34299796, 2021). "Loss of the ATM-ATR signatures also suggest that AML cells with inhibited FOXM1/AKT activity may display higher sensitivity to anti-cancer therapy." (PMID 34381718, 2021). "Furthermore, using the KU55933 treatment, blocking the function of ATM in these cancer cells caused the increase of radiosensitivity because the cells cannot repair the damage caused by homologous recombination repair." (PMID 33912571, 2021). "ATM mutations are present in approximately 5% of all cancers." (PMID 34298632, 2021). "In fact, ATM mutations may sensitize cancer cells to platinum-derived drugs, as BRCA1/2 mutations do, whereas their implications in objective responses to hormonal therapy or target-based agents are not well defined." (PMID 34068084, 2021). "Regarding those genes involved in germline predisposition to other cancers, ATM, APC, POLD1 or SDHC could be promising candidate genes for germline GC predisposition." (PMID 33525650, 2021). "Antioxidants can prevent intrinsic defects and cancer susceptibility in ATM-deficient mice." (PMID 34208940, 2021). "Furthermore, it has been found that ATR inhibitors are selectively toxic to cancer cells harboring mutations in the ATM tumor suppressor, in part because ATM and ATR share some overlapping targets." (PMID 33888558, 2021). "Carcinoma deficient of ATM frequently displays chemotherapy resistance and poor survival." (PMID 33980813, 2021).
cancer (continued). "Because several ATM substrates are key effectors of the cell cycle, cells from A-T patients display defective cell-cycle checkpoints, resulting in genomic instability and cancer predisposition." (PMID 32858941, 2020). "Here, we demonstrate that the combination therapy could be expanded to treat ATM-deficient cancers with the complete loss of protein or function." (PMID 32444694, 2020). "Thus, our findings demonstrate a strong causal relationship between endogenous TOP2-induced DSBs and cancer development, confirming these lesions as major drivers of ATM-deficient lymphoid malignancies, and potentially other conditions and cancer types." (PMID 32060399, 2020). "Moreover, surveillance for other cancers for which ATM is a medium penetrance predisposition gene (for instance, BC) is still under debate and discussion." (PMID 32325837, 2020). "Indeed, a deficiency in ATM inhibition has been associated with carcinogenesis, resistance to DNA damage–induced cancer treatment, and loss of mitotic checkpoint." (PMID 32203529, 2020). "Importantly, the highest doses (3 μM olaparib + 1 μM AZD6738) only caused moderate (39%) growth inhibition in WT cells (Fig. 1aii), suggesting a therapeutic window in ATM-deficient cancers." (PMID 32444694, 2020). "Further analysis of WES data revealed additional variants in common cancer‐related genes involved in DNA replication and DNA damage (e.g., ATM, CDKN1A), cell polarization (SCRIB), proliferation (RNASEL), VEGF expression (MAP3K1, MAP3K6), and in genes encoding growth factors (FGF2) (Table EV2)." (PMID 32667137, 2020). "Furthermore, p21 forms a positive feedback loop with ATM, and this interaction has been shown to underlie the apoptosis resistance of cancer cells that have undergone SIPS following treatment with chemotherapeutic agents." (PMID 32075223, 2020). "Moreover, the incidence of cancers is significantly higher in patients with heterozygous or homozygous ATM mutations compared to individuals with the wild-type ATM gene." (PMID 32329754, 2020). "Previously, loss of PTEN was shown to sensitise various cancer cells to ATM inhibition." (PMID 33396656, 2020). "Moreover, ATM loss is frequently reported in cancers and has been shown to cause a “mild” HR deficiency." (PMID 32664581, 2020). "Despite olaparib and ATR inhibitors demonstrating various degrees of monotherapy efficacy in ATM-deficient cancers, our work highlights the importance of exploring their use in combination through the potential to optimise lower doses and shorter treatment periods due to synergistic activity." (PMID 32444694, 2020). "Indeed, DNA-PK inhibitors have previously been demonstrated to increase lethality in cancers with ATM loss." (PMID 32664581, 2020). "Moreover, deleted regions affecting FCA D1 included genes validated as cancer variants by the CGC59 including ATM validated as somatic-CNL, and tumour suppressor WT1 validated somatic- and germline-CNL." (PMID 31969654, 2020). "In summary, we provide a causal link between endogenously occurring TOP2-induced DSBs and cancer development, putting forward these lesions as important contributors to T-cell malignancies related to ATM loss, and opening the door for their potential involvement in other conditions and cancer types." (PMID 32060399, 2020). "Conversely, activation of ATM is linked to the survival of cancer cells following therapy." (PMID 32203529, 2020). "Homozygous germline mutations in ATM (ataxia-telangiectasia mutated) cause ataxia telangiectasia (A-T), a recessive genetic disease characterized by cerebellar degeneration, chromosomal instability and cancer predisposition." (PMID 32309213, 2020).
cancer (continued). "Furthermore, somatic mutations of ATM have been identified in many cancer types, most commonly lymphoid malignancies, suggesting that ATM loss contributes to tumorigenesis." (PMID 32309213, 2020). "As such, individuals with a pathogenic germline ATM variant are potential candidates for clinical surveillance to identify cancers early before they have spread, and surgical intervention may be curative." (PMID 31963441, 2020). "Rs189037 (G > A) is located at the 5’UTR of ATM gene and is one of the critical polymorphism that may be related to the occurrence of different cancers and tumor diffusing capacity." (PMID 30709340, 2019). "Results indicated a significant association of ATM rs189037 with cancer risk." (PMID 31201228, 2019). "Therefore, we carried out this updated meta-analysis, aiming to use more refined data to clarify the effects of ATM rs189037 on cancer risk stratified by smoking status." (PMID 31201228, 2019). "Three deleterious missense variants of ATM gene were associated with an increased risk of cancer." (PMID 30709340, 2019). "Therefore, we have performed a new meta-analysis of the ATM rs189037 polymorphism and the risk of different cancer types that includes more recent research." (PMID 30709340, 2019). "Another ATM variant identified in our cancer cohort was the pathogenic c.5932G>T variant." (PMID 31882575, 2019). "Rs189037 (G > A) is a functional single nucleotide polymorphism (SNP) in the Ataxia-telangiectasia mutated (ATM) gene that may be associated with the risk of cancer." (PMID 30709340, 2019). "There are clear examples with germline mutations in genes like adenomatous polyposis coli (APC), cadherin 1 (CDH1), BRCA1, von Hippel-Lindau tumor suppressor (VHL), and ataxia telangiectasia mutated (ATM) which are causative for the development of cancer in specific types of tissue." (PMID 31001323, 2019). "Until now, the role of ATM rs189037 in cancer risk stratified by smoking status still remains unclear." (PMID 31201228, 2019). "Together, these results suggest that the combination of a PARP inhibitor with an ATR inhibitor may have significance for the treatment of patients with ATM-deficient cancers." (PMID 31481733, 2019). "Some meta-analyses have made efforts to evaluate the role of ATM rs189037 in cancer risk." (PMID 31201228, 2019). "The BRIP1 mutation c.847T>C and the CHEK2 mutation c.695G>T were found in one of the 504 cancer cases (each) and the ATM mutations c.1595G>A and c.5750G>A were found in two cases (each) of the 710 healthy controls and in six and three cases, respectively, of the 504 cancer cases." (PMID 29659569, 2018). "In order to comprehensively evaluate the impact of ATM rs1801516 polymorphism on cancer risk, we performed TSA to reduce the risk of type I error and to estimate whether further studies are required by calculating the required information size." (PMID 30384829, 2018). "A genetic test for ATM may thus be offered to them and their relatives and thereby direct those individuals towards effective cancer risk management and therapeutic strategies." (PMID 29665859, 2018). "It has been hypothesized for a long time that higher cancer predisposition of A-T patients depends exclusively on defects in ATM-dependent-DDR, which leads to genomic instability." (PMID 29616191, 2018).
cancer (continued). "Mutation on ATM leads to the human autosomal recessive disorder, ataxia-telangiectasia (A-T), resulting in high cellular radiosensitivity, chromosomal instability, immunodeficiency, and cancer predisposition." (PMID 30384829, 2018). "While case 7 has a personal and family history of cancers that could be associated with a germline ATM mutation, most affected relatives tested positive for the familial BRCA mutation, explaining the cancer history in these individuals." (PMID 29659587, 2018). "Considering that rs189037 may regulate the ATM expression, it is meaningful for us to evaluate its association with cancer risk." (PMID 29928473, 2018). "Finally, our data indicate that CC-115 preferentially inhibits the survival of ATM-deficient cancer cell lines, suggesting patients with ATM-deficient cancers as a potential patient population for CC-115." (PMID 29088817, 2017). "Looking deeper at the ATM mutation, it might be visible in the ‘Molecular Mechanisms of Cancer’ (p-value 0.0199) pathway." (PMID 28522871, 2017). "Ataxia telangiectasia mutated (ATM) gene mutations may confer increased sensitivity to ionizing radiation and increased risk of late toxicity for cancer patients." (PMID 28929041, 2017). "Hence, ATM gene polymorphisms are thought to influence the risk of cancer and radiation-induced pneumonitis (RP) risk in cancer patients treated with radiotherapy." (PMID 29246212, 2017). "This further indicates that polymorphisms of the ATM gene may be involved in cancer initiation and progression through multiple pathways." (PMID 28642860, 2017). "It will be interesting to see whether this association between cancer cell stemness and spDSB-induced ATM activation also occurs in more tumor types." (PMID 28337983, 2017). "Human cancers often switch off ATM, either by completely deleting the enzyme or mutating it." (PMID 27304073, 2016). "However, a considerable proportion (~70%) of the ATM mutations reported in cancer to date are missense changes, which lead to the substitution of a single amino acid." (PMID 27602502, 2016). "However, a systematic meta-analysis found that ATM mutation carriers have a reduced lifespan due to cancer (breast and gastrointestinal tract) and ischemic heart disease." (PMID 27884168, 2016). "We hypothesized that the additional DNA repair defects in AtmKD/- cells would confer hypersensitivity to certain genotoxic chemotherapy that could be used to target ATM-mutated cancers." (PMID 27304073, 2016). "We assumed that the difference of radiosensitivity between normal and cancer cells may be the cause of the different responses of ATM to LDR." (PMID 27708248, 2016). "Whether these predicted modifications alter ATM function/s and cancer predisposition remain to be evaluated." (PMID 27599564, 2016). "Finally, immunoblotting confirmed the expression of catalytically inactive ATM protein in several human cancer cell lines with missense mutations around the kinase domain (CCLE, Broad Institute)." (PMID 27304073, 2016).
cancer (continued). "Notably, somatic mutations in the ATM gene have been reported in a broad range of human cancers including colorectal, breast and haematopoietic cancers as well as in 5.1-9.1% of lung cancer cases." (PMID 27602502, 2016). "However, previous research showed that IL-8 is a target gene of ATM pathway in response to cancer-cell associated oxidative stress, which has a tumor promoting role in breast cancers." (PMID 27412620, 2016). "Firstly, given that most cancer-associated ATM mutations are missense variants whose functional consequences have not yet been elucidated, we performed phenotypic studies in a panel of seven NSCLC cell lines, which have been reported to harbour missense changes in the ATM gene." (PMID 27602502, 2016). "Since one of the major DNA repair mechanisms, homologous recombination, is compromised due to loss of ATM in these tumour subsets; this may drive reliance of these cancer cells on the remaining DDR pathways to survive inflicted DNA damage." (PMID 27527858, 2016). "ATM encodes a DNA damage protein that is faulty in some cancers." (PMID 26802434, 2016). "To test this hypothesis, we queried The Cancer Genome Atlas (TCGA) clinical database for the expression of MAPK7 mRNA in human cancers presenting mutated ATM." (PMID 27793024, 2016). "Together, these findings further expand the therapeutic options for ATM mutated cancers." (PMID 27304073, 2016). "Loss of ATM function confers sensitivity to ionising radiation (IR) and topoisomerase inhibitors and may thus define a subset of cancer patients that could get increased benefit from these therapies." (PMID 27602502, 2016). "ATM has important functions in DNA repair and maintenance of genomic integrity and understandably, loss of ATM could be associated with initiation and cancer progression." (PMID 26275218, 2015). "The ATM gene ranked third in terms of mutation frequency in a recent analysis of 518 protein kinases in 210 human cancers; therefore, other kinases may compensate for ATM loss of function." (PMID 25894690, 2015). "Moreover, the contribution of ATM gene mutations to cancer susceptibility is deemed to a bright lamp of cancer epidemiology." (PMID 25541996, 2014). "In view of the connection between loss of ATM activity and increased cancer risk, it may also be informative to determine whether ATM protein levels are reduced in models where retinoids increase cancer risk." (PMID 28250390, 2014). "Furthermore, MSeA can activate ataxia-telangiectasia mutated (ATM) and the catalytic subunit of DNA-dependent protein kinase (DNA-PKcs), two critical DNA damage response kinases, in cancer cells." (PMID 25010594, 2014). "Another possible exploitation of ATM inhibition in cancer therapy is linked to the idea that ATM kinase inhibition may be synthetically lethal with the inhibition of other components of the DDR." (PMID 24681585, 2014). "Interestingly, the analysis of data from the Catalogue of Somatic Mutations in Cancer (COSMIC) identified ATM mutations or deletions in about 5% of about 9000 samples of all types of solid tumors included in this catalogue." (PMID 24681585, 2014).